CDK8 (cyclin dependent kinase 8)
Diseases named in the same sentence as CDK8 in open-access papers (continued):
Sharing a sentence is not in itself a finding about the gene and the disease.
infection (8 papers, 2016 to 2025). The state of being infected such as from the introduction of a foreign agent such as serum, vaccine, antigenic substance or organism. "In agreement with their increased susceptibility, med16 and cdk8 showed the largest number of changed metabolite levels at both 24 and 72 h after infection." (PMID 38514763, 2024). "cdk8 displayed elevated levels of JMT before infection but in contrast to med16 and med25, it showed the same fold-induction of JMT as Col-0." (PMID 38514763, 2024). "Mediator subunits MED8, MED15, MED16, MED18, MED20, MED25 and CDK8 were identified as important for diverse types of infection responses." (PMID 38514763, 2024). "Glucosinolate, phytoalexin and carbohydrate levels were reduced already before infection in med16 and cdk8, but increased in med25, which also displayed increased benzenoids levels." (PMID 38514763, 2024). "The same impairment was detected for med16 after infection whereas cdk8 showed accumulation of JAZ6." (PMID 38514763, 2024). "For this, we treated CD4+ T cells from normal donors with the CDK8/19 inhibitors or a vehicle control prior to infection with the replication incompetent RGH dual-reporter virus." (PMID 37671866, 2023). "For this, we treated cells with the CDK8/19 inhibitors 4 days post infection and measured the proportion of latently and productively infected cells 24 h later." (PMID 37671866, 2023). "This is expected as we are examining BFP expression for the whole of integrated proviruses and the results mirror the effect of CDK8 KO on the productive infection ratio for the indicated treatment." (PMID 37671866, 2023). "Infection induces CDK8 expression, and CDK8 activity is required for the up-regulation of metabolic genes." (PMID 35446926, 2022). "Together, these features of cdk8 infection would yield delayed dissemination to the brain and a prolonged disease course where mortality is primarily determined by a relatively rare, stochastic BBB crossing event." (PMID 30755515, 2019). "In Candida albicans, disruption of Cdk8 and other Mediator elements alters regulation of virulence in a murine infection model (19, –, 22)." (PMID 30755515, 2019). "Finally, oxylipins with conjugated OPDA were induced in all lines, but most prominently in Col-0, med16 and cdk8 at the early time point after infection." (PMID 38514763, 2024). "The sensitive med16 and cdk8 mutants displayed increased jasmonate levels after infection." (PMID 38514763, 2024). "In contrast, cdk8 showed low Camalexin levels both before and after infection." (PMID 38514763, 2024). "However, the productive proviral infections of CDK8 KO cells following incubation with a vehicle control, JQ1, or IACS-9571 displayed greatly reduced LTR expression as compared to wildtype (Productive)." (PMID 37671866, 2023). "However, our infection results show that cdk8 at 72 h after infection contains twice as many bacteria compared to med16 but we could not detect any clear difference for these metabolite categories between the two mutants." (PMID 38514763, 2024). "In addition, we examined whether treatment of cells with the CDK8/19 inhibitors post infection affected the proportion of latent or productively infected cells." (PMID 37671866, 2023). "Wildtype (WT) or CDK8 KO Jurkat T cells were infected with RBH, and the populations were subsequently treated with a vehicle control (Ve) or an LRA 4 days post infection; flow cytometry was performed 1 day later to examine BFP and mCherry expression." (PMID 37671866, 2023). "QRT-PCR analysis revealed that at early stage of infection (day 1 p.i.), mRNA levels of cell cycle genes such as CDC2, CDC25A, Cyclin E, CDK5, CDK8 and Cyclin G1 were significantly (P<0.05) upregulated in A. phagocytophilum-infected cells in comparison to uninfected controls." (PMID 28797056, 2017).
infection (continued). "Confocal microscopic analysis shows that CDK8 was redistributed and recruited to IE62+ replication compartments upon infection whether or not cells were pretreated with IFN-α." (PMID 26985360, 2016).
blood cancer (3 papers, 2019 to 2021). "We describe a kinase-independent function of CDK8 in hematopoietic tumors and suggest that the proteasome-induced degradation of CDK8 in combination with inhibition of mTOR might represent an addition to the therapeutic armory." (PMID 31628323, 2019). "Promoters with relatively increased Med1 and Cdk8 are enriched for chromatin organization and immunity-related genes in the MM1S blood cancer cell line, for differentiation and apoptosis genes in human embryonic stem cells (hESCs), and stress responses in HCT116 cells." (PMID 34515029, 2021).
cardiovascular disease (3 papers, 2025 to 2026). "Among genes where AS affected the domain structure, we also found CDK8 (cyclin-dependent kinase 8) and SRC (SRC proto-oncogene, non-receptor tyrosine kinase), which are associated with cardiovascular disease and cardiac remodeling, respectively." (PMID 40337913, 2025).
hematologic malignancies (3 papers, 2015 to 2024). "Related studies have reported that overexpressed CDK8 contributes to the development of colorectal, breast and hematologic malignancies by activating Wnt-β-catenin signaling." (PMID 38460002, 2024).
colorectal (2 papers, 2010 to 2021). "We recently characterized CDK8 as a colorectal oncogene that functions as part of the Mediator complex to modulate β-catenin-driven transcription." (PMID 20126544, 2010).
neurodevelopmental disorder (2 papers, 2018 to 2020). A behavioral and cognitive disorder with onset during the developmental period that involves impaired or aberrant development of intellectual, motor, or social functions. "A recent study reported that heterozygous missense CDK8 mutations cause a neurodevelopmental disorder in humans." (PMID 33067521, 2020). "Other Mediator subunits, including other CDK8-kinase module-associated disease genes, have been associated with various neurodevelopmental disorders." (PMID 29740699, 2018).
bacterial infections (1 paper, 2023). "The current study aimed to explore CDK8/19-dependent immune responses in viral and bacterial infections." (PMID 37376593, 2023). "Together with the reports that CDK8/19 inhibition suppresses the replication of other viruses, our findings suggest that CDK8/19 inhibitors may be broadly beneficial for the treatment of different viral and bacterial infections and potential immunomodulators." (PMID 37376593, 2023).
Colon (1 paper, 2011). "Colon cancer cell line HCT116 was transfected with small interfering RNA (siRNA) targeting on CDK8." (PMID 22104393, 2011).
CDK8 also shares sentences with these, for which no sentence is quoted: glioblastoma (3 papers); breast tumors (2); liver cancer (2); medullary thyroid cancer (2); skin tumor (2); adenoma (1); breast invasive ductal carcinoma (1); chronic lymphocytic leukemia (1); colon adenocarcinoma (1); congenital heart disease (1); dengue virus infection (1); depression (1); developmental and epileptic encephalopathy (1); diabetic retinopathy (1); dilated cardiomyopathy (1); Epileptic encephalopathy (1); esophageal adenocarcinoma (1); esophageal cancer (1); Ewing sarcoma (1); fibrosarcoma (1); Focal cortical dysplasia (1); graft-vs.-host disease (1); hematopoietic tumors (1); hypertrophic cardiomyopathy (1); idiopathic pulmonary fibrosis (1); inflammatory bowel disease (1); laryngeal squamous cell carcinoma (1); Lewis lung carcinoma (1); liposarcoma (1); lung squamous cell carcinoma (1).
A further 26 diseases each share a sentence with CDK8 in 1 paper.